EGFR (epidermal growth factor receptor)
Diseases named in the same sentence as EGFR in open-access papers (continued):
Sharing a sentence is not in itself a finding about the gene and the disease.
respiratory diseases (9 papers, 2008 to 2022). "In conclusion, the data presented here indicate activation of EGFR signaling by WCS exposure promotes respiratory disease by causing ciliated cell loss and inhibiting ciliated cell replacement leading to reduced MCC and inefficient host defense." (PMID 27532261, 2016). "Therefore, aesculetin targeting TLR4 and EGFR may find use in treating airborne PM-associated respiratory diseases." (PMID 33809902, 2021). "EGFR itself has a leading role in the regulation of the inflammation and can mediate innate immune responses in airway epithelium in respiratory diseases." (PMID 21364874, 2011). "These lines of evidence suggest that cigarette smoking may exacerbate respiratory diseases and carcinogenesis via N-arylation of EGFR." (PMID 33705793, 2021). "Among them, representative respiratory diseases-related targets included IL-6, IL-10, IL-1β, TNF-α, interferon (IFN)-γ, epidermal growth factor (EGF) and its receptor (EGFR), TNF-α, transforming growth factor (TGF)-β1, etc." (PMID 31530860, 2019). "The epidermal growth factor receptor (EGFR) is a member of the erythroblastic oncogene B (ErbB)/HER family of receptors regulating lung homeostasis and respiratory diseases." (PMID 30258361, 2018).
cardiac diseases (8 papers, 2016 to 2023). "This study suggests that targeting EGFR may provide useful therapeutic strategies for cardiac diseases and these two novel EGFR inhibitors 542 and 543 may be promising for the further drug development." (PMID 26762600, 2016). "EGFR and MMP-9 contribute to neointimal proliferation in SP shunts of children with complex cyanotic heart disease." (PMID 36867212, 2023).
immune diseases (8 papers, 2020 to 2025). "In conclusion, EGFR plays a dual role in the regulation of inflammatory process in immune diseases and in the development of cutaneous complications upon EGFRIs chemotherapy." (PMID 39966897, 2025). "EGFR transactivation contribute to cartilage destruction and EGFR inhibitor is also an common drug targets for immune disorders." (PMID 33992108, 2021). "The findings of our study suggest that treatments could be developed for TNFR1-related immune diseases by employing EGF or EGFR agonists in a future clinically valid trial." (PMID 38789573, 2024).
infectious disease (8 papers, 2016 to 2025). A disorder directly resulting from the presence and activity of a microbial, viral, or parasitic agent in humans. "Understanding the complex interplay between viruses and EGFR in host cells is paramount for devising effective strategies to combat infectious diseases." (PMID 38136637, 2023).
brain disease (7 papers, 2013 to 2025). "As the mature iPFS was lacking, a long‐term follow‐up is needed to verify the survival benefit with dacomitinib in EGFR‐mutated NSCLC patients with brain disease." (PMID 34751504, 2021). "A further clinical trial will be needed to explore the best strategy for brain disease in patients with EGFR‐positive NSCLC." (PMID 34751504, 2021). "Among 32 patients with EGFR‐mutated NSCLC and brain disease, eight were included in the CNS evaluable for response group." (PMID 34751504, 2021). "Although diffuse glioma is often described as a network-level brain disease, the tract-wise FA findings in our cohort point to selective, left-hemispheric changes associated with EGFR amplification (AF and FAT), rather than diffuse whole-brain involvement." (PMID 40941753, 2025).
blood cancer (6 papers, 2020 to 2024). "As the epidermal growth factor receptor (EGFR) is a subject of common oncogenic alterations in GBM, we tested anti-EGFR therapy combined with temozolomide (first-choice medication for GBM) or with doxorubicin (common therapeutic for various solid and blood cancers)." (PMID 36900355, 2023).
colon polyps (6 papers, 2015 to 2024). "Tjalma and colleagues used vascular endothelial growth factor A (VEGF-A) and EGFR as targets and irdye800cw as a fluorescent agent for the detection of colonic polyps." (PMID 37781571, 2023). "Meanwhile, a high-risk score was correlated with increased age, history of colon polyps, right half of CRC, dMMR as well as EGFR mutation." (PMID 34898475, 2021). "Previous molecular studies show increased epidermal growth factor receptor (EGFR) and COX signaling in colon polyps." (PMID 38609520, 2024).
hematopoietic cancers (6 papers, 2017 to 2025). "Compared to hematological cancers, solid tumors such as OSCC had more than 80% higher EGFR expression levels." (PMID 34885013, 2021).
gastrointestinal disorders (5 papers, 2016 to 2025). "In the gastrointestinal disorders, the combination of EGFR inhibitor and gemcitabine was more toxic compared to gemcitabine alone, with the increased risk of vomiting (OR: 2.96; 95% CI: 1.42–6.15; p = 0.004; heterogeneity: I2 = 0%)." (PMID 31703359, 2019). "Additionally, the ROR for gastrointestinal disorders caused by Afatinib was significantly higher than that for other EGFR-TKIs, and the ROR for cardiac disorders caused by Osimertinib was markedly higher than that for other EGFR-TKIs." (PMID 40135231, 2025). "Additionally, Afatinib-induced gastrointestinal disorders had a significantly higher ROR025 than other EGFR-TKIs, and Osimertinib-induced cardiac disorders had a notably higher ROR025 compared to other EGFR-TKIs." (PMID 40135231, 2025).
gastrointestinal disease (4 papers, 2022 to 2025). A disease that occurs in the gastrointestinal system, excluding the hepatobiliary system. "Numerous studies have suggested that EGFR (epidermal growth factor receptor) is closely associated with gastrointestinal diseases." (PMID 39624840, 2024). "Gastrointestinal diseases are common in many oral TKIs acting on EGFR and VEGF." (PMID 36505840, 2022).
retinal disorder (3 papers, 2020 to 2025). Any disease or disorder of the retina. "EGFR inhibition has been linked to reduced fibrotic remodeling in retinal disorders, while MAPK3 signaling plays a context-dependent role in cell survival and differentiation." (PMID 40508210, 2025). "Similarly, the EGFR inhibitor erlotinib reduced pathological neovascularization in an oxygen-induced retinopathy (OIR) mouse model by inhibiting ADAM17 and EGFR." (PMID 40391004, 2025).
central nervous system disease (2 papers, 2015 to 2025). "Numerous studies have shown that endogenous Lingo1 plays critical roles in negatively regulating the EGFR/PI3K/Akt signaling pathway in the pathophysiology of central nervous system disorders by reducing EGFR levels through direct physical interactions." (PMID 39781463, 2025).
gynecologic tumors (2 papers, 2019 to 2024). "We evaluated lineage-specific drug sensitivity in gynecologic tumors and discovered that EOCs demonstrated enhanced sensitivities to multiple EGFR inhibitors, while ECs were particularly sensitive to everolimus, an mTOR inhibitor." (PMID 31771620, 2019).
EGFR also shares sentences with these, for which no sentence is quoted: psychiatric disorder (14 papers); bronchioloalveolar carcinoma (10); Hodgkins lymphoma (9); prion disease (9); idiopathic pulmonary fibrosis (8); pilocytic astrocytoma (8); chronic gastritis (7); mental retardation (7); pulmonary TB (7); autoimmune thyroid disease (6); bipolar disorder (6); genetic disorders (6); Huntington disease (6); hypertrophic cardiomyopathy (6); Myocardial fibrosis (6); thalassemia (6); acute lung injury (5); acute myocardial infarction (5); autism (5); Chagas disease (5); esophagitis (5); herpes simplex infection (5); leishmaniasis (5); myxofibrosarcoma (5); non-alcoholic fatty liver disease (5); Parkinson (5); acute promyelocytic leukemia (4); American trypanosomiasis (4); CADASIL (4); cardiac arrhythmias (4).
A further 419 diseases each share a sentence with EGFR in 4 papers or fewer.